TIRAP (TIR domain containing adaptor protein)
Diseases named in the same sentence as TIRAP in open-access papers (continued):
Sharing a sentence is not in itself a finding about the gene and the disease.
diabetes (3 papers, 2009 to 2015). "Hence, diabetes-associated vascular damages through AGE-RAGE interaction are probably mediated by TIRAP and MyD88." (PMID 21829704, 2011). "It is relevant to note that resveratrol, known for its cardioprotective, anti-cancer, anti-oxidant, anti-inflammatory, anti-diabetes, anti-obesity, anti-Alzheimer and anti-Parkinson effects, also suppresses the expression of TIRAP, and a similar effect may be expected from BRP." (PMID 26660901, 2015).
liver fibrosis (3 papers, 2023 to 2026). "In addition, TIRAP is also involved in the development of liver fibrosis and promotes extracellular matrix accumulation by regulating the activation and proliferation of hepatic stellate cells." (PMID 39462099, 2024).
lymphoma (3 papers, 2022). A malignant (clonal) proliferation of B- lymphocytes or T- lymphocytes which involves the lymph nodes, bone marrow and/or extranodal sites. "TIRAP was reported to be an upstream regulator of the NF‐κB pathway and its expression enhanced cell proliferation in lymphoma." (PMID 35233921, 2022). "TIRAP polymorphisms were examined for their possible correlations with cancer risk (lymphoma, glioma, and NHL), but none of these correlations have yet been confirmed." (PMID 36011276, 2022).
non-small cell lung carcinoma (3 papers, 2019 to 2023). A group of at least three distinct histological types of lung cancer, including non-small cell squamous cell carcinoma, adenocarcinoma, and large cell carcinoma. "In terms of TIRAP, another PRG in the PPS, it was associated with the proliferation of non-small-cell lung cancer cells, while the knockdown of its expression was found to inhibit cell proliferation." (PMID 35255915, 2022). "In non-small cell lung cancer (NSCLC) cells, downregulating TIRAP can significantly inhibit the proliferation of tumor cells." (PMID 38025749, 2023).
psoriasis (3 papers, 2021 to 2023). An autoimmune condition characterized by red, well-delineated plaques with silvery scales that are usually on the extensor surfaces and scalp. "Furthermore, genetic polymorphisms of TLRs, IL-1β, LY96, and TIRAP have been associated with a response to anti-TNFα or ustekinumab in psoriasis." (PMID 37511413, 2023).
asthma (2 papers, 2018 to 2023). "In addition, the downstream effector of miR-146a-5p, including TNF receptor-associated factor 6 (TRAF6) and TIR domain-containing adaptor protein (TIRAP), which are related to airway epithelial cell injury and airway inflammatory response in asthma, were decreased." (PMID 37090722, 2023). "We first examined the relationship of genotype and asthma at the individual SNP/gene level (TLR4, CD14, TIRAP, and TNFα)." (PMID 30140039, 2018).
autoimmune disease (2 papers, 2013 to 2018). A disorder resulting from loss of function or tissue destruction of an organ or multiple organs, arising from humoral or cellular immune responses of the individual to their own tissue constituents. "The present study extends our understanding of TIRAP’s membrane association, which could be helpful in designing peptide decoys to block TLR2-, TLR4-, TLR7-, and TLR9-mediated autoimmune diseases." (PMID 29434596, 2018). "The PBD carries a significant segment, the PBM, that could serve as a decoy to prevent or dissociate TIRAP from the membrane in order to control dysregulated and overexpressed TLR2/TLR4/TLR7/TLR9-dependent autoimmune diseases." (PMID 29434596, 2018).
Autoimmunity (2 papers, 2016 to 2023). The occurrence of an immune reaction against the organism's own cells or tissues. "Our findings highlight a role for Mal outside the TLR system and imply that genetic variation in TIRAP may be linked to other IFN-γ-related diseases including autoimmunity and cancer." (PMID 26885859, 2016). "The protein encoded by this TIRAP gene, is related to the TLR4 signaling pathway and plays an important role not only in innate immunity but also in autoimmunity." (PMID 38028622, 2023).
endometrial cancer (2 papers, 2021 to 2025). Primary or metastatic malignant neoplasm involving the endometrium (mucous membrane that lines the endometrial cavity). "The heatmap in endometrial cancer showed that ELANE and GSDMD were upregulated and GPX4 and TIRAP were downregulated." (PMID 34722500, 2021).
endometriosis (2 papers, 2020 to 2025). The growth of functional endometrial tissue in anatomic sites outside the uterine body. "Compared to normal human endometriosis cells, the expression of BAK1, CHMP2A, GPX4, and GSDMD was upregulated, whereas the expression of CHMP2B, IRF2, and TIRAP was negatively regulated in UCEC cells." (PMID 40535818, 2025).
gram-negative bacterial infections (2 papers, 2018 to 2022). Infections caused by bacteria that show up as pink (negative) when treated by the gram-staining method. "We, therefore, addressed the contribution of TIRAP in the response to Gram-positive and Gram-negative bacterial infections in MDMs and revealed a partial dependency of TIRAP in the regulation of cytokine production with all the examined bacteria." (PMID 35884781, 2022).
immune deficiency (2 papers, 2018 to 2020). "Interestingly, similar results have been described in adult studies where TIRAP polymorphism in its heterozygous S180L form conferred protection against primary immune deficiency, or septic shock." (PMID 30131804, 2018).
lung disease (2 papers, 2013 to 2019). "By contrast, our present results revealed that TIRAP participated in regulating proliferation and apoptosis of multiple NSCLC cells, which further confirmed the important role of TIRAP in different lung diseases." (PMID 31207932, 2019).
Obesity (2 papers, 2015 to 2024). Accumulation of substantial excess body fat. "TIRAP, TNFRSF1A, CASP1, CSF1, and ITGAM are associated with the development of type 2 diabetes, a condition linked to obesity." (PMID 39194753, 2024).
ventilator-associated pneumonia (2 papers, 2010 to 2018). Serious INFLAMMATION of the LUNG in patients who required the use of PULMONARY VENTILATOR. "Combination of TLR4 and TIRAP SNPs has been described to be associated with low circulating levels of TNF-α and IL-6 in adult patients with ventilator-associated pneumonia following 1 ng/ml LPS-stimulation." (PMID 30131804, 2018). "Additionally we found significantly lower circulating cytokine levels in double-mutant individuals with ventilator associated pneumonia and reduced cytokine production in an ex-vivo monocyte stimulation assay, but this difference was not apparent in TIRAP/Mal-homozygous patients." (PMID 20525286, 2010).
abscesses (1 paper, 2020). "A total of 121 patients with major abscesses and 132 with DFIs participating in a randomized clinical trial were genotyped for 13 nonsynonymous single-nucleotide polymorphisms (SNPs) in genes coding for TLRs and the signaling adaptor molecule TIRAP." (PMID 31786695, 2020).
acute lung injury (1 paper, 2010). A condition of lung damage that is characterized by bilateral pulmonary infiltrates (pulmonary edema) rich in neutrophils, and in the absence of clinical heart failure. "Toll like receptors (TLRs) signaling pathways, including the adaptor protein Mal encoded by the TIRAP gene, play a central role in the development of acute lung injury (ALI)." (PMID 21118491, 2010).
arteriosclerosis (1 paper, 2020). A vascular disorder characterized by thickening and hardening of the walls of the arteries. "We measured expression of TLR4, TIRAP, MyD88, TRAF6, p38, NEMO, and IRF5 to test the anti-arteriosclerosis effect of corilagin." (PMID 32849545, 2020).
atherosclerosis (1 paper, 2020). A disease characterized by the build-up of fatty material and calcium deposition in the arterial wall resulting in partial or complete occlusion of the arterial lumen. "Taken together, our observed findings suggest that the involvement of core genes related to the risk of atherosclerosis might be a critical metric in ubiquitin-mediated proteolysis, Toll-like receptor, and MyD88: MAL (TIRAP) cascades and a beneficial tool for diagnosis and targeted therapy." (PMID 32760426, 2020).
breast carcinoma (1 paper, 2021). "Among them, IL-18 [p = 0.015, HR(95%CI): 0.832(0.717–0.965)] was a protective factor as well as GSDMC [p = 0.044, HR(95%CI): 1.120(1.003–1.251)] and TIRAP [p = 0.025, HR(95%CI): 1.336(1.037–1.722)] were risk factors for breast cancer prognoses." (PMID 34589498, 2021). "Our univariate cox regression analyses showed that IL-18 was a protective factor as well as GSDMC and TIRAP were risk factors for breast cancer prognoses." (PMID 34589498, 2021). "As shown in univariate cox regression analyses, IL-18, GSDMC, and TIRAP were significantly associated with survival outcomes of breast cancer." (PMID 34589498, 2021). "A three-gene regression model including IL18, GSDMC, and TIRAP was regarded as an independent risk factor of breast cancer prognoses." (PMID 34589498, 2021). "As depicted in western blotting, IL-18, GSDMC, and TIRAP expression was all markedly up-regulated in breast cancer cells MDA-MB-231 and HCC70 compared with normal breast cells MCF-10A." (PMID 34589498, 2021).
Cerebral ischemia (1 paper, 2022). Restriction of arterial blood supply to the brain associated with insufficient oxygenation to support the metabolic requirements of the tissue. "The detailed mechanism of the protective effects of simple O-substituted isoflavones against cerebral ischemia reperfusion might be related to the PI3K/AKT/ERK/mTOR or GSK-3β pathway, eNOS/Keap1/Nrf-2/HO-1 pathway, TLRs/TIRAP/MyD88/NFκ-B pathway, and Bcl-2-regulated anti-apoptotic pathway." (PMID 36142301, 2022).
cervical cancer (1 paper, 2022). A primary or metastatic malignant neoplasm involving the cervix. "In conclusion, we identified that TIRAP polymorphisms increase the probability for an older age at the time of diagnosis (rs8177376 and rs611953) and lower tumor grade (rs8177376) in cervical cancer." (PMID 36011276, 2022). "To investigate the influence of TIRAP polymorphisms on cervical cancer, we decided to analyze four polymorphisms, rs8177376, rs611953, rs3802814, and rs8177374, that were chosen using the RefSNP Report database (dbSNP) based on their MAF and location in the gene." (PMID 36011276, 2022). "Therefore, this study aimed to analyze TIRAP rs8177376, rs611953, rs3802814, and rs8177374 polymorphisms and to identify their impact on cervical cancer phenotype and prognosis." (PMID 36011276, 2022). "Thus, TIRAP polymorphisms might be employed in the future as potential biomarkers for determining the phenotype and prognosis of cervical cancer." (PMID 36011276, 2022). "Since studies have shown that TLR4, TLR7, and TLR9 play a significant role in HPV recognition, understanding how genetic variations in TIRAP affect signal transduction in TLR pathways and their effects on cervical cancer is crucial." (PMID 36011276, 2022). "There is a lack of knowledge if cervical cancer may be associated with TIRAP gene polymorphisms." (PMID 36011276, 2022).
cervical tumor (1 paper, 2025). "The T allele of the rs8177376 polymorphism in TIRAP is statistically associated with lower cervical tumor grades." (PMID 40538398, 2025).
congenital toxoplasmosis (1 paper, 2017). Toxoplasma infection that is present from birth. "Our sequential analysis of other candidate susceptibility loci presented herein, found that TREX1, TIRAP MAL, FOXQ, and TLR9 also had allelic variants significantly associated with susceptibility to congenital toxoplasmosis in the NCCCTS (p < 0.05)." (PMID 28904337, 2017).
cryptosporidiosis (1 paper, 2021). Intestinal infection with organisms of the genus Cryptosporidium. "This is the first study to indicate an association between TLR4 and TIRAP polymorphisms with cryptosporidiosis." (PMID 34583337, 2021).
cystitis (1 paper, 2009). Inflammation of the urinary bladder. "In order to discover novel polymorphisms associated with UTIs, we PCR-amplified and sequenced the coding regions of 7 TLR pathway genes (TLR2, TLR4, TLR5, MYD88, TIRAP, TRIF, and TRAM) in subjects with a high frequency of cystitis or pyelonephritis episodes." (PMID 19543401, 2009).
fatty liver (1 paper, 2024). "Overall, we found that HOPE plays an important role in alleviating fatty liver IRI by regulating the TFPI2/CLIP1/TIRAP pathway to suppress the inflammatory response in a rat model of severe fatty liver." (PMID 39617791, 2024). "Therefore, our findings suggest that targeting the TFPI2/CLIP1/TIRAP signaling pathway with HOPE could be a potential therapeutic strategy for alleviated IRI in fatty liver transplantation." (PMID 39617791, 2024).
gastric tumors (1 paper, 2023). "Our results confirmed that the expression of GPX4, CASP6, IL-6, CASP5, CASP4, and TIRAP was greatly up-regulated in gastric tumors relative to normal tissues." (PMID 37595258, 2023).
glioblastoma (1 paper, 2023). The most malignant astrocytic tumor (WHO grade IV). "In addition, the TCGA database showed that co‐high expression of ALKBH5 and TIRAP is associated with poor prognosis in patients with glioblastoma and thyroid cancer receiving radiotherapy." (PMID 36792369, 2023).
influenza (1 paper, 2022). An acute viral infection of the respiratory tract, occurring in isolated cases, in epidemics, or in pandemics; it is caused by serologically different strains of viruses (influenzaviruses) designated A, B, and C, has a 3-day incubation period, and usually lasts for 3 to 10 days. "In influenza and in some influenza like infections (such as SARS-CoV-2), genetic polymorphism of TIRAP, an accessory protein of TLR4, attenuates the function of TIRAP, leading to the reduced production of pro-inflammatory cytokines." (PMID 35629310, 2022).
ischemia reperfusion injury (1 paper, 2025). Adverse functional, metabolic, or structural changes in ischemic tissues resulting from the restoration of blood flow to the tissue (reperfusion), including swelling; hemorrhage; necrosis; and damage from free radicals. "In ischemia-reperfusion injury, TFPI2-CLIP1 binding inhibits TIRAP ubiquitination, reducing inflammation." (PMID 40361374, 2025).
latent infection (1 paper, 2025). "miR-181a and miR-29b have been shown to target SLC11A1 and TIRAP, respectively, providing post-transcriptional regulation in latent infection states." (PMID 40565607, 2025).
leprosy (1 paper, 2009). Leprosy is a chronic infectious disease affecting primarily the skin and peripheral nervous system. "We observed heterozygous TIRAP S180L in 11% of control individuals, but more frequently, 22%, in leprosy patients." (PMID 19602285, 2009).
lupus nephritis (1 paper, 2021). Glomerulonephritis in the context of systemic lupus erythematosus.
myocardial ischemia (1 paper, 2023). A disorder of cardiac function caused by insufficient blood flow to the muscle tissue of the heart. "TLR2 signaling is associated with left ventricular dysfunction and activation of the Toll interleukin 1 receptor (TIR) domain-containing adaptor protein (TIRAP) in myocardial ischemia and subsequent reperfusion." (PMID 37893187, 2023).
nephritis (1 paper, 2021). Inflammation of renal tissue. "Moreover, the T allele of TIRAP rs8177374 was higher in LN than in non-nephritis and control subjects." (PMID 34572591, 2021). "Moreover, the TIRAP rs8177374 genotypes CT and TT could also predict nephritis in SLE, with (OR 3.420, p = 0.003) and (OR 3.942, p = 0.006), respectively." (PMID 34572591, 2021). "Moreover, CT + TT of TIRAP was noticeably higher in nephritis patients (54.0%) than in non-nephritis patients (25.5%, OR1 = 3.420, p = 0.003) and controls (18%, OR2 = 5.341, p < 0.001), and no significant distinction was observed between non-nephritis patients and controls (OR3 = 1.562, p = 0.293)." (PMID 34572591, 2021).
prostate carcinoma (1 paper, 2022). A carcinoma that arises from epithelial cells of the prostate gland. "The two clusters showed significant differences in the expression of PRGs; CHMP2A, CHMP4C, CYCS, CASP6, CASP8, GPX4, and TIRAP have high expression levels in cluster B, suggesting that these genes may associate with poor prognosis in prostate cancer." (PMID 35813821, 2022).
Pseudomonas infection (1 paper, 2017). Infections with bacteria of the genus pseudomonas. "PumA ensures efficient inhibition of innate immune responses by interacting with MyD88 and TIRAP, key adaptor proteins for IL‐1R and the main relevant TLRs in Pseudomonas infection (TLR4 and TLR5), as well as UBAP1 which regulates cytokine receptor pathways." (PMID 28483816, 2017).
pulmonary tuberculosis (1 paper, 2008). A bacterial infection that affects the lungs and is caused by Mycobacterium tuberculosis. "In brief, we found previously that the TIRAP SNP C558T and the TLR-2 SNP T597C were associated with susceptibility to meningeal rather than pulmonary tuberculosis and this was reconfirmed in the current dataset." (PMID 18369480, 2008).
rectum adenocarcinoma (1 paper, 2022). An adenocarcinoma arising from the rectum. "In contrast, TIRAP is a protective gene in KIRC, rectum adenocarcinoma (READ), and STAD but a risk gene in only BRCA." (PMID 35246158, 2022).
respiratory failure (1 paper, 2022). The significant impairment of gas exchange within the lungs resulting in hypoxia, hypercarbia, or both, to the extent that organ tissue perfusion is severely compromised. "The proportion of carriage of TIRAP polymorphism was also markedly higher in patients without respiratory failure, although not statistically significant." (PMID 34995294, 2022).
rheumatoid arthritis (1 paper, 2012). A chronic, systemic autoimmune disorder characterized by inflammation in the synovial membranes and articular surfaces. "TLRs also promote the inflammatory and destructive processes in rheumatoid arthritis with adapters MyD88 and MAL/TIRAP having a significant role." (PMID 23305364, 2012).
type 2 diabetes (1 paper, 2024). "DAVID was used to identify the functions of these genes, and TIRAP, TNFRSF1A, CASP1, CSF1, and ITGAM were associated with type 2 diabetes." (PMID 39194753, 2024).